LEPR (leptin receptor)
Diseases named in the same sentence as LEPR in open-access papers (continued):
Sharing a sentence is not in itself a finding about the gene and the disease.
Obesity (continued). "The aim of the present study was todetermine the possible association of five single-nucleotide polymorphisms (SNPs)located in the IGF2, LEPR, POMC,PPARG, and PPARGC1genes with obesity orobesity-related risk phenotypes." (PMID 25923461, 2015). "In the current study, PCOS and the obesity status increases leptin level and decresaes the soluble leptin receptor." (PMID 26180527, 2015). "The cerebellum shows strong leptin receptor gene expression and is activated by circulating leptin and diet-induced obesity, which forms a monitoring/signaling pathway to complement more direct hypothalamic interactions." (PMID 26039080, 2015). "Four common variants involved in inflammatory-adipokine triggering (IL6 rs2069845, LEPR rs1137100, NAMPT rs3801266, and AMD1 rs2796749) have recently been associated with obesity and related traits in Indian children." (PMID 26558825, 2015). "Homozygous leptin receptor null rats are characterized by obesity, hyperphagia, hyperglycemia, glucose intolerance, hyperinsulinemia and dyslipidemia." (PMID 26537785, 2015). "The relationship between the decrease in leptin sensitivity in the brain and the development of insulin resistance was shown in patients with obesity, MS and T2DM having the Gln223Agr and Asp100Tyr mutations in gene encoding leptin receptor OBRb." (PMID 28031898, 2015). "Monogenic mutations such as those described for LEP, LEPR, POMC, and MC4R cause only a minority of obesity cases whereas in most individuals obesity is based on a polygenic predisposition amplified by an obesogenic Western lifestyle." (PMID 26470795, 2015). "Second, leptin receptor mutant animals demonstrated lower circulating and tissue NK cell numbers and impaired NK cell function as well as prominent obesity and insulin resistance." (PMID 25224267, 2014). "Among the most widely used animal models in obesity-induced type 2 diabetes mellitus (T2DM) research are the congenital leptin- and leptin receptor-deficient rodent models." (PMID 24809394, 2014). "Although humans don't carry the same mutation in leptin receptor as the obese JCR rats, leptin resistance does occur and is known to be associated with obesity in humans." (PMID 25222487, 2014). "Variants at the CTNNBL1, LEPR and PPARG loci demonstrated nominal association with obesity phenotypes (meta-analysis P-values ranging from 1.15×10−3 to 4.94×10−2)." (PMID 24879436, 2014). "There are several studies indicating links of leptin gene (LEP) and leptin receptor gene (LEPR) variations with obesity, insulin resistance, and type 2 diabetes." (PMID 24444121, 2014). "Overexpression of SK1 in breast cancer cells was shown to promote cell growth, and our data show for the first time its regulation by LEPR, which functionally links obesity and breast cancer." (PMID 25482303, 2014). "Over the past 15–20 years, mutations in a number of genes including leptin (LEP), leptin receptor (LEPR), pro-opiomelanocortin (POMC) and melanocortin-4 receptor (MC4R) have been associated with monogenic obesity." (PMID 23306188, 2013). "Studies have indicated that variations in the leptin receptor gene exist across ethnic populations, but the relationship between these variations and obesity and metabolic morbidity is inconclusive." (PMID 23940841, 2013). "The ZDF rat which has a missense mutation in the gene coding the leptin receptor (fa/fa) spontaneously develops insulin resistance, T2DM, hyperlipidemia, both moderate hypertension and obesity, and progressive renal injury." (PMID 23844375, 2013). "Due to the direct connection between obesity and type 2 diabetes, molecular targets that often link these two diseases were assessed beginning with leptin receptor signaling." (PMID 24260287, 2013). "Recently, it has been shown that knockout of leptin receptor in Nos1-positive neurons produces obesity similar to ob/ob mice." (PMID 24251118, 2013).
Obesity (continued). "In the animal studies, leptin receptor mutant db/db mouse is a widely used diabetes model presenting hyperglycemia, hyperlipidemia, obesity, and desensitization of insulin signaling pathway." (PMID 24489534, 2013). "Coding DNA sequences of the known genes of obesity like leptin and leptin receptor seems to be unaltered in this animal model." (PMID 24204914, 2013). "It has been shown recently that knockout of leptin receptor in Nos1-positive neurons produces obesity similar to ob/ob mice, which indicates that these neurons are the major sites of leptin signaling." (PMID 24251118, 2013). "A recent study showed that mice null for the leptin receptor (LepRb) specifically in neurotensin neurons showed early-onset obesity, modestly increased feeding, and decreased locomotor activity." (PMID 23620827, 2013). "First, it has been demonstrated that obesity in BBS mice was associated with hyperleptinemia and LepR." (PMID 22927860, 2012). "Zucker fa/fa rats are a spontaneous monogenic model of obesity as a result of a dysfunctional leptin receptor." (PMID 22808093, 2012). "Employing functional candidate analysis, we recently identified association of common variants of IL6, LEPR, and PBEF1 with increased susceptibility to obesity and measures of adiposity in Indian children." (PMID 22496743, 2012). "However, it is not known whether genetic variants in genes encoding fat and obesity-associated (FTO), leptin (LEP), and leptin receptor (LEPR) associate with physical performance, and whether fitness level modifies the risk for obesity associated with these gene variants." (PMID 23284729, 2012). "ZF rats are hyperphagic due to the defect of leptin receptor, which leads to the development of obesity, insulin resistance, hyperinsulinemia and hyperlipidemia." (PMID 23028851, 2012). "Fewer studies reported an association between LEP 19 A>G, LEPR 233Q>R and risk of NHL in Chinese populations, though some previous published studies revealed that obesity was a risk factor of NHL in developed countries." (PMID 22666399, 2012). "Heterozygosity for deleterious coding mutations in MC4R or POMC has been associated with a non fully penetrant form of obesity, whereas partial LEP or LEPR deficiency has been associated with a higher percentage of body fat mass." (PMID 22043164, 2011). "One commonly studied candidate gene for obesity, the leptin receptor gene (LEPR), is on a biologic pathway to obesity (leptin-insulin pathway)." (PMID 22028824, 2011). "For example, mouse BBS proteins are required in the hypothalamus to regulate leptin receptor trafficking and to prevent the onset of obesity." (PMID 22022287, 2011). "Recessive forms of obesity caused by homozygous / heterozygous compound loss of function mutations in five genes (LEP, LEPR, POMC, PCSK1 and MC4R) have been reported to date." (PMID 22043164, 2011). "The finding extends the current understanding of the functions of leptin receptor isoforms, and suggests OBRe as a potential target in the management of obesity and related disorders." (PMID 20652026, 2010). "In animal models, deletion of the cerebral leptin-receptor leads to obesity and elevated plasma levels of leptin, glucose, and insulin." (PMID 20871818, 2010). "As a result of this genetic leptin receptor resistance, Zucker rats show severe metabolic alterations, including severe obesity, hyperglycemia, hyperinsulinemia, insulin resistance, and hypogonadism." (PMID 20592755, 2010). "Covey and colleagues report that mice with deletion of leptin receptor in pancreatic β cells and hypothalamus develop obesity, fasting hyperinsulinemia, impaired glucose-stimulated insulin release, and glucose intolerance." (PMID 21113299, 2010). "To further examine the effect of HS+MES on another mouse model of type 2 diabetes, we used 6-week-old male db/db mice, which exhibit defects in leptin receptor and develop obesity because of hyperphagia and decreased energy expenditure." (PMID 19114996, 2008).
Obesity (continued). "High LEP levels in children with obesity, and their dependence on adipose tissue content, may suggest the presence of leptin resistance related to an altered leptin receptor/post-receptor pathway in this group." (PMID 40586327, 2025). "Altogether, our data provides for the first time evidence that disruption of leptin receptor signaling leading to obesity and T2DM induces altered type I interferon and cell-mediated responses against SARS-CoV-2, mediating increased viral replication and delayed clearance." (PMID 40125513, 2025). "In total, our results reveal ArcGABA non-LepR neurons as an alternative neural basis for leptin resistance and effective therapeutic target against obesity and suggest that improving cellular leptin resistance alone may not be able to reduce DIO." (PMID 40540394, 2025). "Additionally, early investigations demonstrated that obesity and high-fat diet intake markedly reduce specific leptin transporters, including the expression of the short leptin receptor isoform, ObRa, in brain endothelial cells." (PMID 41516046, 2025). "Similarly, other components of the leptin–melanocortin axis, including LEP, LEPR, POMC, PCSK1, and SIM1, have been associated with both monogenic and polygenic obesity." (PMID 41226372, 2025). "It has been shown that diet-induced obesity reduced the expression of leptin receptor in the liver of rats, whilst the upregulation of hepatic leptin receptor induced by metformin reduced lipogenic gene expression and decreased hepatic triglyceride content, alleviating liver steatosis." (PMID 41373837, 2025). "Our current results suggest that HFD feeding induced activation of Arc non-LepR neurons and that activation of these non-LepR neurons, in turn, caused massive obesity." (PMID 40540394, 2025). "Although rare monogenic obesity syndromes (e.g., those caused by mutations in the LEP gene, leptin receptor gene (LEPR), melacortin 4 receptor (MC4R), and fat mass and obesity-associated gene (FTO)) provide valuable information about the pathways regulating body weight." (PMID 41150735, 2025). "However, our findings are consistent with previous studies of other BBSome genetic knockouts (Bbs2–/– and Bbs4–/–), which demonstrate that dysregulated leptin receptor signaling is a key ciliopathy-mediated disruption contributing to obesity in BBS." (PMID 40233116, 2025). "Although the loss of PI3Kγ protects mice from diet-induced obesity, it does not reduce adiposity in leptin-deficient mice or mice lacking a functional leptin receptor." (PMID 39811649, 2025). "Therefore, in the context of human obesity, although serum levels of leptin are typically elevated, there is a diminishment in the endocrine and paracrine effects of leptin due to leptin resistance at the leptin receptor, analogous to obesity-related IR." (PMID 39997710, 2025). "Because selective deletion of leptin receptor in neurons phenocopy the overt obesity observed in ob/ob and db/db mice, we reasoned that the obesogenic action of PI3Kγ may also depend on its activity in neurons." (PMID 39811649, 2025). "Setmelanotide is another anti-obesity medication; however, it has been approved only for three ultra-rare genetic disorders that cause obesity: Pro-OpioMelanoCortin (POMC) deficiency, Proprotein Convertase Subtilisin and Kexin type 1 (PCSK1) deficiency, and LEPtin Receptor (LEPR) deficiency." (PMID 40806889, 2025). "Interestingly, chronic inhibition of Arc non-LepR neurons prevented body weight gain and reversed obesity in DIO mice." (PMID 40540394, 2025). "Important genes associated with monogenic obesity consist of leptin (LEP), leptin receptor (LEPR), proopiomelanocortin (POMC), prohormone convertase 1 (PCSK1), MC4R, single-minded homolog 1 (SIM1), brain-derived neurotrophic factor (BDNF), and its receptor NTRK2 (commonly referred to as TrkB)." (PMID 40428329, 2025).
Obesity (continued). "We then followed the body weight for an additional 8 weeks on an HFD and found that the Kir2.1 mice showed significantly reduced obesity development compared to the control group, suggesting that chronic inhibition of Arc non-LepR neurons is sufficient to reverse DIO." (PMID 40540394, 2025). "Although multiple melanocortin receptor agonists have been investigated, setmelanotide is currently the only MC4R agonist approved by the FDA for the treatment of specific genetic forms of obesity, including deficiencies in POMC, PCSK1, and LepR, as well as Bardet-Biedl syndrome (BBS)." (PMID 41016636, 2025). "The recent approval of Setmelanotide, an MC4R agonist, for treating obesity caused by deficiencies in proopiomelanocortin (POMC), proprotein convertase subtilisin/kexin type 1 (PCSK1), or Leptin Receptor, has heightened scientific interest in the effects of MCRs on feeding and energy balance." (PMID 39974186, 2025). "A recent study identified six proteins (LEPR, IGFBP1, WFIKKN2, AGER, DPT, and CTSA), including WFIKKN2, which may have a causal role in the development of obesity." (PMID 39273278, 2024). "Obesity could also have an impact on the observed mechanisms, as adipose derived leptin increases with fat mass gain and signals through the leptin receptor via the JAK/STAT pathway." (PMID 38880827, 2024). "Notably, individuals with the CLOCK (CC), FTO (AA), and LEP (AA) genotypes exhibited the highest BMI and WHR, while those with GHRL (TT), MC4R (CC), and LEPR (GG) genotypes, although showing lower values, were still correlated with overweight and obesity." (PMID 39203789, 2024). "In contrast, in African-American children, higher methylation of the LEPR gene was associated with average weight and showed a negative relationship with obesity measures." (PMID 39766314, 2024). "To evaluate whether the impaired glucose tolerance and insulin action in BNC2 LepR knockout mice was a direct effect or secondary to their obesity, we modulated the activity of BNC2 neurons using chemogenetics." (PMID 39478220, 2024). "Similarly, the long-term outcomes of bariatric surgery were evaluated in patients with bi-allelic mutations in known monogenic obesity genes such as POMC, LEPR, and MC4R." (PMID 38469147, 2024). "Methodology: Utilizing leptin receptor mutant (SSLepR mutant) rats as a genetic model of obesity, 11–12-week-old male and female lean Dahl salt-sensitive (SS) rats and obese SSLepR mutant rats were used to investigate sex differences in obesity-induced periodontal inflammation." (PMID 39851590, 2024). "The first one, setmelanotide, was approved in 2020, and it is used in patients with POMC, PCSK1, or leptin receptor (LEPR) deficiencies, which result in insufficient activation of the MC4R and, consequently, cause excessive appetite and severe obesity developing in early childhood." (PMID 39125772, 2024). "Type 2 diabetes in males of this strain results from polygenic interactions producing a moderate obesity rather than the massive obesity elicited by mutations in the leptin or leptin receptor axis, such as ob/ob or db/db mice." (PMID 38444587, 2024). "Moreover, the genetic aspect of obesity, particularly the role of specific polymorphisms in genes like obesity-associated (FTO), leptin (LEP), leptin receptor (LEPR), and melanocortin 4 receptor (MC4R) genes, has been extensively studied." (PMID 38398881, 2024). "Obesity, characterized by an imbalance between energy consumption and expenditure, coupled with resistance to leptin, correlates with diminished signaling through the leptin receptor (LEPR)." (PMID 38398810, 2024). "The drug is specifically indicated for patients with decreased POMC, PCSK1, or leptin receptor (LEPR) or patients diagnosed with a rare genetic syndrome called Bardet-Biedl syndrome that presents with cognitive delays, short stature, and obesity in the pediatric population." (PMID 39559664, 2024).
Obesity (continued). "Mouse models lacking specific key BBS proteins develop hyperphagia and obesity associated with reduced LEPR signaling and mistrafficking of the receptor to the plasma membrane." (PMID 36647077, 2023). "Monogenic obesity is caused by variants of only one gene, and several genes have been associated with this type of obesity, such as leptin (LEP), leptin receptor (LEPR), pro-opiomelanocortin (POMC), and melanocortin 4 receptor gene (MC4R), which is the most common form of monogenic obesity." (PMID 38003013, 2023). "In patients with obesity due to BBS, POMC deficiency, or LEPR deficiency, hyperphagia is associated with impaired health-related quality of life (HRQOL), with patients reporting guilt, frustration, sadness, and feelings of failure given the inability to control their hunger." (PMID 36647077, 2023). "In both male and female mice, T cell-specific leptin receptor deficiency did not reverse impaired glucose tolerance in obesity, although it did prevent impaired fasting glucose levels in obese mice compared to littermate controls, in a sex dependent manner." (PMID 37276236, 2023). "Since increased Cdc42 and MMP-2 activity are observed in obesity and aging, it is conceivable that increased Cdc42 activity may lead to the degradation of the leptin receptor and affect leptin transport to the brain." (PMID 38068822, 2023). "Here, we show that the LepR-expressing portal neurons send GABAergic projections to a cohort of α3-GABAA receptor expressing neurons within the dorsomedial hypothalamic nucleus (DMH) for the control of leptin-mediated obesity phenotype." (PMID 37043384, 2023). "The most frequent causes of monogenic obesity are mutations in the genes leptin (LEP), leptin receptor (LEPR), melanocortin 4 receptor (MC4R), proopiomelanocortin (POMC), proprotein convertase subtilisin/kexin type 1 (PCSK1), and neurotrophic receptor tyrosine kinase 2 (NTRK2)." (PMID 37375898, 2023). "Further, Necdin and Magel2 together were shown to control leptin receptor sorting and degradation through a ubiquitin-dependent pathway, including E3 ubiquitin ligase Rnf41, deubiquitinase Usp8, and protein Stam1, contributing to obesity in PWS." (PMID 37685915, 2023). "Biallelic, (likely) pathogenic variants in LEP encoding leptin and LEPR encoding its receptor, leptin receptor (LEPR), that follow highly penetrant Mendelian inheritance lead to a congenital LEP-signaling-deficient state, causing very-early-onset severe obesity due to persistent hyperphagia." (PMID 37659411, 2023). "Finally, we examined the impact of CM-specific LIPTER transgene on cardiomyopathy of leptin-receptor-deficient Leprdb/db mouse, a model of T2DM and obesity that develops cardiac hypertrophy and dysfunction from 10 weeks of age42,43." (PMID 37264180, 2023). "To test whether LAT1 in LepR-expressing neurons contributes to metabolic response to diet-induced obesity, we weekly measured body weight of LepR-Cre Slc7a5fl/fl mice switched to HFD at 7 weeks of age." (PMID 36862514, 2023). "We chose the widely used leptin receptor knockout (db/db) mouse model, in which the lack of leptin signaling causes persistent hyperphagia, obesity, beta-cell dysfunction, and insulin resistance and diabetes." (PMID 36901964, 2023). "To this end, we selectively reexpressed Slc7a5 in LepR-expressing neurons by stereotaxically and bilaterally microinjecting a Cre-inducible adeno-associated virus (AAV), AAV-hSynI-DIO-Slc7a5-mCherry (AAV-Slc7a5), into the VMH of LepR-Cre Slc7a5fl/fl mice before the onset of obesity." (PMID 36862514, 2023). "In 2020, the Food and Drug Administration (FDA) approved the first treatment involving the MC4R agonist setmelanotide for chronic weight management in adult and pediatric patients at least 6 years of age with obesity due to three rare genetic conditions: POMC, LEPR, or PCSK1 deficiency." (PMID 37571382, 2023).